ATP11A (ATPase phospholipid transporting 11A)
Diseases named in the same sentence as ATP11A in open-access papers (continued):
Sharing a sentence is not in itself a finding about the gene and the disease.
pulmonary fibrosis (3 papers, 2021 to 2025). Chronic progressive interstitial lung disorder characterized by the replacement of the lung tissue by connective tissue, leading to progressive dyspnea, respiratory failure, or right heart failure. "This supports our observation that ATP11A is a key gene in differential immune cell infiltration in patients with APH or PH alone, suggesting that ATP11A may act as a susceptibility gene for pulmonary fibrosis and an indicator of pulmonary hypertension." (PMID 34823498, 2021). "We use colocalization and transcriptomic analyses to identify shared genetic variants, likely causal genes including ATP11A and DPP9, and important cellular contexts for critically ill COVID-19 and idiopathic pulmonary fibrosis." (PMID 39876559, 2025). "These genes were identified in reports of the alternative splicing in pulmonary fibrosis of known etiologies CD44, RXFP1, and CD146, a pulmonary fibrosis mouse model (FGFR2), and a genetic link between COVID-19 and IPF (DP99 and ATP11A)." (PMID 39937013, 2025).
diabetes (2 papers, 2023 to 2024). "Similarly, Soranzo and colleagues have shown that ATP11A is significantly associated with the levels of HbA1c, which is used to monitor diabetes." (PMID 36870961, 2023).
hearing loss (2 papers, 2022 to 2025). "Mutations in ATP11A have been described in individuals with sensorineural hearing loss and neurological deterioration; however, little is known regarding the mechanism by which loss of atp11a results in such phenotypes." (PMID 40223426, 2025). "We report a new DFNA gene, ATP11A, in a Newfoundland family with a variable form of bilateral sensorineural hearing loss (SNHL)." (PMID 35278131, 2022). "Subsequently, 202 NL probands with hearing loss were screened wild-type for ATP11A chr13:113534963G>A." (PMID 35278131, 2022). "Although other phospholipid flippases (P4-ATPases) are associated with syndromic forms of hearing loss, this study documents the first association of ATP11A with a highly penetrant Mendelian phenotype." (PMID 35278131, 2022). "The disease mechanism, how variants in the ATP11A gene cause hearing loss, is unclear." (PMID 35278131, 2022).
hepatocellular carcinoma (2 papers, 2017 to 2024). A malignant tumor that arises from hepatocytes. "TMEM30A and ATP11A were therefore overexpressed in two different human tumor cell lines, hepatocellular carcinoma SMMC-7721 and cervical adenocarcinoma HeLa." (PMID 28640862, 2017).
inflammatory bowel disease (2 papers, 2021 to 2023). A spectrum of small and large bowel inflammatory diseases of unknown etiology. "Among these genes, Dusp4, Epha2, Atp11a, and Tns4 are reported to be overexpressed in human CRC, while the expression of Thbs1 is increased in patients with inflammatory bowel disease." (PMID 37296911, 2023).
autosomal dominant deafness-84 (1 paper, 2025). "ATP11A is associated with autosomal dominant deafness-84 (DFNA84; MIM #619810), an NSHL form, characterized by a slow progression, typically with onset in the first or second decade of life." (PMID 41007806, 2025).
brain inflammation (1 paper, 2024). "ELISA data demonstrated that siATP11A significantly increased the expression of IL-6 and TNF-α, while ATP11A overexpression significantly reduced the expression levels of IL-6 and TNF-α, indicating that ATP11A overexpression may alleviate brain inflammation." (PMID 39664587, 2024).
breast carcinoma (1 paper, 2021). "The result indicated that the DSVs in SNTG2, PCMT1, DACT2, CBX3, ATP11A, and SHC2 were associated with breast cancer." (PMID 33431054, 2021).
chronic lung disease (1 paper, 2021). According to the definitions of the American and British Thoracic Societies, including pulmonary functional tests, X-rays, and CT scans for items such as fibrosis, bronchiectasis, bullae, emphysema, nodular or lymphomatous abnormalities. "Overall, the function of this protein and results from previous genetic studies are consistent with ATP11A playing an important role in chronic lung diseases." (PMID 33808877, 2021).
Cognitive impairment (1 paper, 2024). Abnormal cognition is characterized by deficits in thinking, reasoning, or remembering. "Therefore, we hypothesized that Atp11a may be closely related to the decline in learning and memory abilities and cognitive impairment observed in early AD." (PMID 39664587, 2024).
congenital heart disease (1 paper, 2022). A heart disease that is present at birth. "We identified DMRs overlapping MYRF and ATP11A which are both genes directly associated with congenital heart disease including BAV." (PMID 35711915, 2022).
deafness (1 paper, 2025). An inherited or acquired condition characterized by the complete loss of the ability to hear from one or both ears. "Zebrafish atp11a mutants were created to model deafness, given the description of four families with hearing loss segregating with ATP11A mutations." (PMID 40223426, 2025). "As mutation of ATP11A results in sensorineural hearing loss in human pedigrees we sought to create an atp11a mutant zebrafish to model human deafness." (PMID 40223426, 2025).
developmental delays (1 paper, 2024). "Previous studies have shown that mutations in ATP11A cause developmental delays and neurological deterioration 55, and ATP11A participate in the formation of the syncytiotrophoblast layer during placental development." (PMID 39664587, 2024).
gallstones (1 paper, 2021). Solid crystalline precipitates in the biliary tract, usually formed in the gallbladder, resulting in the condition of cholelithiasis. "Both miR-210 and its target ATPase phospholipid transporting 11A (ATP11A) are dysregulated in human gallstones, and ATP11A expression is negatively correlated with miR-210 expression in patients with the disease." (PMID 33665015, 2021).
gastric cancer (1 paper, 2024). A primary or metastatic malignant neoplasm involving the stomach. "Firstly, we found that ATP11A was abnormally expressed in gastric cancer tissues and cells, and was associated with poor prognosis." (PMID 39247595, 2024). "This study aimed to identify ATP11A related to the biological behavior of gastric cancer, and elucidate the underlying mechanism." (PMID 39247595, 2024). "We further used calibration analysis to predict the association of ATP11A expression with 1, 2, and 3-year prognosis in gastric cancer patients." (PMID 39247595, 2024). "Then, we proved that ATP11A is associated with poor prognosis of gastric cancer." (PMID 39247595, 2024). "Through additional experiments, we discovered that ATP11A can affect the invasive ability of gastric cancer cells." (PMID 39247595, 2024). "In this study, we first analyzed the expression of ATP11A in TCGA and GTEx databases, and found that ATP11A was overexpressed in gastric cancer tissues compared with normal tissues." (PMID 39247595, 2024). "In summary, our study showed that the expression of ATP11A in gastric cancer tissues was higher than that in normal tissues." (PMID 39247595, 2024). "The ROC curve showed that ATP11A had excellent predictive ability to distinguish gastric cancer, with an area under the curve of 0.954 (95% CI=0.940-0.969)." (PMID 39247595, 2024). "We further explored the effect of ATP11A on the prognosis and clinical significance of gastric cancer." (PMID 39247595, 2024). "The IHC results showed that ATP11A was upregulated in gastric cancer tissues than in adjacent gastric cancer tissues, and the expression of ATP11A in gastric cancer cells from high to low is BGC-823, MGC-803, HGC-27 and SGC-7901 cells." (PMID 39247595, 2024). "In summary, the results indicated that ATP11A can devitalize Hippo signaling to promote EMT in gastric cancer cells." (PMID 39247595, 2024). "Subsequently, we demonstrated that ATP11A promoted the migration, invasion and proliferation of gastric cancer cells." (PMID 39247595, 2024). "Furthermore, we explored the role of ATP11A on the proliferation of gastric cancer cells through CCK-8 and colony formation assays." (PMID 39247595, 2024). "ATP11A was correlated with poor prognosis of gastric cancer." (PMID 39247595, 2024). "In addition, western blotting and qRT-PCR were performed to confirm the role of ATP11A in gastric cancer cell invasion." (PMID 39247595, 2024). "The present study indicated that ATP11A expression was higher in gastric cancer tissues than normal tissues, and bioinformatic analysis showed that the high expression of ATP11A was related to poor prognosis in patients with gastric cancer." (PMID 39247595, 2024). "Hence, we proposed that ATP11A facilitated the malignant progression of gastric cancer cells via the Hippo/YAP pathway." (PMID 39247595, 2024). "Hence, we aimed to explore the association between ATP11A and migration, invasion, proliferation and EMT in gastric cancer cells." (PMID 39247595, 2024). "Additionally, we proved that ATP11A promoted the migration, invasion and proliferation in gastric cancer cells." (PMID 39247595, 2024). "Our study suggested that ATP11A might be a candidate target for the diagnosis and prognosis of gastric cancer." (PMID 39247595, 2024). "Mechanistically, ATP11A promoted EMT by Hippo pathway in gastric cancer cells." (PMID 39247595, 2024). "In this study, we focused on the role of ATP11A in gastric cancer for the first time." (PMID 39247595, 2024). "Therefore, we hypothesized that ATP11A might promote EMT in gastric cancer cells through Hippo pathway." (PMID 39247595, 2024). "It is suggested that ATP11A may play an oncogene role in gastric cancer." (PMID 39247595, 2024). "Our study revealed that ATP11A may act as a key role in gastric cancer progression." (PMID 39247595, 2024). "Additionally, we provided evidence that ATP11A could induce EMT in gastric cancer cells." (PMID 39247595, 2024).
gastric cancer (continued). "However, the role of ATP11A in gastric cancer remains unknown." (PMID 39247595, 2024). "Subsequently, we demonstrated that ATP11A promoted the migration, invasion, proliferation and EMT of gastric cancer cells." (PMID 39247595, 2024). "However, the role of ATP11A in gastric cancer remains unclear." (PMID 39247595, 2024). "The data from the present study proved that ATP11A promoted the migration, invasion, proliferation and EMT of gastric cancer cells." (PMID 39247595, 2024). "Secondly, we overexpressed and knocked down ATP11A in different gastric cancer cell lines, and no animal experiments were performed to verify the cytological results." (PMID 39247595, 2024). "However, the relationship between ATP11A and EMT in gastric cancer remains unclear." (PMID 39247595, 2024).
lung adenocarcinoma (1 paper, 2024). A carcinoma that arises from the lung and is characterized by the presence of malignant glandular epithelial cells. "Further comparison of ATP11A expression between tumors in single cell public database (Cancer Single‐cell Expression Map) showed that ATP11A was highly expressed in STAD, Thyroid carcinoma (THCA) and Lung adenocarcinoma (LUAD) amongst other tumors." (PMID 39247595, 2024).
Obesity (1 paper, 2022). Accumulation of substantial excess body fat. "Even though ATP11A’s involvement in obesity and T2D is unknown, there is evidence that deficient expression of some P4 ATPase family members, such as ATP10C and ATP10A, affects insulin-stimulated mobilization of GLUT4 vesicles to the plasma membrane or the regulation of insulin signaling." (PMID 36535927, 2022).
schizophrenia (1 paper, 2024). A major psychotic disorder characterized by abnormalities in the perception or expression of reality. "The ATP11A genes might also underlie the genetic connection between schizophrenia and T2DM." (PMID 39202552, 2024).
staphylococcus aureus infection (1 paper, 2024). An infectious process in which the bacteria Staphylococcus aureus is present. "For KEGG, ATP11A mainly enriched in Protein digestion and absorption, Pancreatic secretion, Neuroactive ligand-receptor interaction, Olfactory transduction and Staphylococcus aureus infection." (PMID 39247595, 2024).
type 2 diabetes (1 paper, 2014). "Sites annotated to 10 candidate genes for type 2 diabetes, including DUSP9, BCL11A, HNF4A, and CDKN2B, and 7 candidate genes for related metabolic traits (for example, ATP11A, ADCY5 and IRS1) had differential DNA methylation in human pancreatic islets based on sex." (PMID 25517766, 2014).
cancer (6 papers, 2016 to 2024). A tumor composed of atypical neoplastic, often pleomorphic cells that invade other tissues. "The relative expression of ATP11A in cancer tissues and adjacent tissues were explored." (PMID 39247595, 2024).
tumor (4 papers, 2017 to 2024). "Our results indicate that TMEM30A and ATP11A promote the migration of tumor cells, which is consistent with reports that depletion of either TMEM30A or ATP8A1 causes a severe defect in cell migration." (PMID 28640862, 2017). "ATP11A has been reported to be involved in different biological processes of tumor cells." (PMID 39247595, 2024).
infection (1 paper, 2024). The state of being infected such as from the introduction of a foreign agent such as serum, vaccine, antigenic substance or organism. "Variants within the ATP11A gene influence the development of illness requiring hospitalization after infection with SARS-CoV-2." (PMID 38400850, 2024).
inherited diseases (1 paper, 2024). "ATP11C and ATP11A have also been linked to inherited diseases." (PMID 38436085, 2024).
ATP11A also shares sentences with these, for which no sentence is quoted: basal cell carcinoma (1 paper); cervical adenocarcinoma (1); colon cancer (1); heart failure (1); idiopathic pulmonary fibrosis (1); infectious disease (1); lung carcinoma (1); pancreatic adenocarcinoma (1); progressive familial intrahepatic cholestasis type 1 (1); pulmonary hypertension (1); sensorineural hearing loss (1); Stargardt disease (1); stomach adenocarcinoma (1); Thyroid carcinoma (1).